NPY6R (neuropeptide Y receptor Y6 (pseudogene) )
Synonyms: NPY1RL; PP2; Y2B; NPY6RP
Gene: Long non-coding RNA gene on chromosome 5 (137,801,192 to 137,860,070, forward strand). Ensembl gene ENSG00000293504.
Diseases named in the same sentence as NPY6R in open-access papers:
NPY6R is named in the same sentence as 9 diseases in open-access papers, as found by Europe PMC text mining. Sharing a sentence is not in itself a finding about the gene and the disease. The quoted sentences say what the papers report.
disc degeneration (1 paper, 2022). "Npy6r expression is correlated with disc degeneration and has shown to increase expression in AF cells when exposed to inflammatory stimuli." (PMID 35186933, 2022).
Hypertension (1 paper, 2022). The presence of chronic increased pressure in the systemic arterial system. "In addition, NPY6R, one of the adrenergic candidate sites, may play a role in autonomic/sympathetic dysfunction in the hypertension." (PMID 35432628, 2022).
uveal melanoma (1 paper, 2022). A melanoma derived from melanocytes of the uveal tract. "This study investigated the expression and prognostic significance of neuropeptide Y receptor Y6 (NPY6R) in uveal melanoma (UVM) and preliminarily investigated the biological function of NPY6R in UVM." (PMID 35432628, 2022).
tumor (2 papers, 2022). "GSEA suggested that NPY6R expression was associated with tumor progression in UVM." (PMID 35432628, 2022). "Gene set enrichment analysis suggested that NPY6R is associated with tumor progression in UVM." (PMID 35432628, 2022). "NPY6R is involved in the tumor progression of UVM and has a good predictive value as a prognostic marker of UVM." (PMID 35432628, 2022). "NPY6R was significantly associated with the characteristics of the UVM immune microenvironment and was involved in UVM tumor progression." (PMID 35432628, 2022). "Correlation analysis between NPY6R expression and tumor immune infiltration suggested that NPY6R expression was significantly and positively correlated with the infiltration of T-helper, Tcm, pDC, and CD8 T cells." (PMID 35432628, 2022). "In contrast, the HRs of CCT7P1 and NPY6R were less than 1, suggesting that they may inhibit tumour progression." (PMID 36127676, 2022).
NPY6R also shares sentences with these, for which no sentence is quoted: bladder cancer (1 paper); cancer (1); colon cancer (1); colorectal cancer (1); infection (1).